STK39 (serine/threonine kinase 39)
Diseases named in the same sentence as STK39 in open-access papers (continued):
Sharing a sentence is not in itself a finding about the gene and the disease.
cancer (21 papers, 2013 to 2025). A tumor composed of atypical neoplastic, often pleomorphic cells that invade other tissues. "We found that STO phenocopied the effect of STK39 deficiency and inhibited cancer cell migration and invasion in vitro." (PMID 34335956, 2021). "Previous study showed that the expression of STK39 was associated with the development of multiple types of cancer." (PMID 34519635, 2021). "Three (ITGAX, STK39 and C6) are found to be associated with aggressive cancer in GWAS and QTL studies." (PMID 29738578, 2018). "In this study, we show that the WNK1-OXSR1/STK39 pathway regulates amino acid uptake and controls mTORC1 signalling, suggesting that the pathway plays an essential role in regulating cancer cell metabolism." (PMID 40425534, 2025). "The STK39 is expressed at high levels in normal human testes and the prostate, as well as in several cancer cell lines." (PMID 37371576, 2023). "The expression of STK39 is related to the occurrence of various human diseases, including hypertension, Parkinson’s disease and multiple types of cancer." (PMID 34519635, 2021). "The levels of STK39 are increasing in diverse types of cancer." (PMID 34519635, 2021). "And the expression of STK39 is also related to the malignant degree of some cancers." (PMID 34519635, 2021). "In recent years, a growing body of literature has shown the roles of STK39 in human cancers." (PMID 34281492, 2021). "Because of its unique structural organization and important roles in regulating blood pressure, kidney disease, and cancer, STK39 is an active drug target that may hold future promise." (PMID 34335956, 2021). "Indeed, compounds that inhibit STK39 activity have been developed and show promise as a potential anti-cancer drugs 48-50." (PMID 34335956, 2021). "As human homologues of the murine pre-diagnostic antigens exist and the proteins appear to be expressed in human pre-invasive breast lesions, we explored the potential utility of three of the antigens, Pdhx, Otud6B, and Stk39 in discriminating women who would eventually develop cancer from controls." (PMID 24886063, 2014). "Besides, the abnormal expression of STK39 also affects the progression of cancers." (PMID 34281492, 2021). "Therefore, targeting WNK1-OXSR1/STK39 pathway provides a potential strategy for targeting amino acid metabolism in AML therapy and could be leveraged for treating other types of cancer as well." (PMID 40425534, 2025). "However, there are no clinically-approved drugs that target STK39 being used to treat cancer." (PMID 34335956, 2021).
infection (5 papers, 2013 to 2024). The state of being infected such as from the introduction of a foreign agent such as serum, vaccine, antigenic substance or organism. "Using CD19+ peripheral B cells from independent donors, we reproducibly saw that infection with EBNA3A-REV virus (considered wild type [WT]) resulted in a rapid reduction of STK39 mRNA level." (PMID 29367247, 2018). "STK39 was quickly silenced after infection of primary B cells by EBV." (PMID 29367247, 2018). "After establishing that STK39 was robustly repressed by EBNA3A, we investigated what was happening early after infection of primary B cells with EBV." (PMID 29367247, 2018).
STK39 also shares sentences with these, for which no sentence is quoted: ischemic stroke (10 papers); Gitelman syndrome (8); glioma (8); Hydrocephalus (8); Stroke (8); Hyperkalemia (7); pseudohypoaldosteronism type 2 (6); Gordon syndrome (4); epilepsy (3); neurological diseases (3); autism (2); colitis (2); edema (2); Hypocalciuria (2); infertile (2); inflammatory bowel disease (2); Polyuria (2); acute lung injury (1); alcoholic hepatitis (1); Alkalosis (1); alopecia (1); Anxiety (1); artery stenosis (1); autism spectrum disorder (1); brain disorder (1); breast tumor (1); cardiomyopathy (1); cardiovascular disease (1); Central diabetes insipidus (1); Cerebral ischemia (1).
A further 38 diseases each share a sentence with STK39 in 1 paper.